CTLA4 (cytotoxic T-lymphocyte associated protein 4)
Diseases named in the same sentence as CTLA4 in open-access papers (continued):
Sharing a sentence is not in itself a finding about the gene and the disease.
tumor (continued). "Combinatorial treatment of bacteria and anti-PDL1, or anti-CTLA4, elicited an anti-tumour response shown by reduced tumour size and increased T cell activation in these animals." (PMID 34658896, 2021). "More importantly, systemic administrations of anti-PD-1 + anti-CTLA-4 Abs with PL1-OX40 (ψ) + anti-OX40 Ab dramatically reduced the tumor metastasis in the lung metastasis model." (PMID 34907171, 2021). "Tumor growth is accompanied by immune escape, which is facilitated by immune checkpoint molecules, such as CTLA-4, PD-1/PD-L1/2, and LAG3." (PMID 34768716, 2021). "CD4 T-cell help was critical to achieve the optimal expansion and cytolytic activity of tumor-reactive CD8 T cells in the context of vaccination with tumor neoantigens, or immune checkpoint blockade with anti-PD-1 and/or anti-CTLA-4." (PMID 34201655, 2021). "In the past, CTLA-4 has been found to be limited to T cells but nowadays, evidence reveals CTLA-4 expression in tumor cells." (PMID 33906311, 2021). "Combo CPI and anti-CTLA4 alone had the strongest impact on tumor growth, with anti-PD1 alone having a less dramatic but still significant impact on growth." (PMID 34632444, 2021). "The ability of the tumor microenvironment to control cancer progression has been leveraged by checkpoint inhibitors such as anti PD-1 or anti CTLA-4-directed antibodies." (PMID 34944891, 2021). "Flow cytometry data of T cell frequencies indicated significant activation Tem (CD44hiCD62Llo) and reduced ratios of Treg to Teff in auto-reactive CD4 T cells, however, humanized clones of CTLA-4 antibody had similar anti-tumor efficacy and improved safety." (PMID 33571254, 2021). "When coupled with anti-PD-1 to abrogate the PD-1/PD-L1 inhibitory axis, and anti-CTLA-4 to maximize immunotherapeutic potency (e.g. by priming the immune system), enhanced survival and tumour growth control was seen." (PMID 34229458, 2021). "Accordingly, triple combination therapy (OV/PD-1/CTLA-4) was shown to significantly prolong survival in PDAC tumour-bearing mice." (PMID 34733287, 2021). "This indicated that an intact commensal microbiome is required to develop effective anti-tumor responses following treatment with anti-CTLA-4 antibody." (PMID 34162429, 2021). "Compared to ADT combined with anti-CTLA-4 alone, this triple combination resulted in delayed castration resistance, reduction in tumor volume and significantly increased survival." (PMID 33800156, 2021). "Although CTLA-4 plays a crucial role in prevention of autoimmunity, its activity can often contribute to evasion of anti-tumor immunity in cancer." (PMID 33801964, 2021). "Antibodies that specifically block the CTLA-4 or PD-1/PD-L1 pathway have the potential to remove T cell immune suppression enabling the successful recognition and killing of tumor cells." (PMID 33859638, 2021). "ICB agents, in the form of antibodies, binding to these ligands/receptors (anti-CTLA-4 and anti-PD-1/anti-PD-L1) can overcome inhibitory signaling and reactivate T-cell engagement toward the tumor." (PMID 33888558, 2021). "In tumor bearing mouse models, this action of CTLA-4 blockade translates into the expansion of both CD4 + and CD8 + effector T cells in the tumor microenvironment (TME)." (PMID 33602280, 2021). "Significant anti-tumor activity was demonstrated using variable doses of anti-CTLA-4 and anti-PD-1 antibodies." (PMID 33571254, 2021). "In a recent study of an animal model of mesothelioma, tumor resident regulatory T-cells were shown to co-express high levels of CTLA-4 and OX40 on a large proportion of cells." (PMID 33952230, 2021). "Exhausted (terminal differentiation) CD8+ T cells (cluster 10 in Paratumor and cluster 0 in Tumor) were enriched with exhaustion genes CTLA4, PDCD1 and HAVCR2." (PMID 33429363, 2021). "Anti-CTLA4 monoclonal antibodies constrain Tregs immune suppression in the tumor microenvironment and enhance CD4+ and CD8+ T cells primary and memory function." (PMID 34899700, 2021).
tumor (continued). "To this end, we performed TCR sequencing on isolated CD8+ TILs and splenic CD27lo CX3CR1−, CD27hi CX3CR1−, and CX3CR1+ CD8+ T cells from MC38 tumor-bearing mice treated with combined anti-CTLA-4/PD-L1 therapy." (PMID 33658501, 2021). "Given the increase in tumor parenchyma-infiltrating SPAS-1+ CD8+ T cells in refractory tumors following combination IRE + anti-CTLA-4 therapy, we also wondered if these tumor-specific T cells adopted characteristics of tissue-resident memory cells." (PMID 34162858, 2021). "For example, by activating CTLA-4, PD-1, and PD-L1 inhibitory signals, cancer cells can subvert or disarm immune regulatory pathways, leading to increased tumor survival." (PMID 34675810, 2021). "Individually targeting OX40 generated an effective response against tumor development, and was found to be synergistic with anti-CTLA4 agents." (PMID 33952230, 2021). "CD3 is a direct T-cell marker, and the antibody [89Zr]DFO-CD3 was shown to predict xenograft tumor model anti-CTLA-4 therapeuty response." (PMID 33920423, 2021). "Across several tumor types, the proportion of activated NK cells was positively correlated with CTLA-4 expression, while the proportion of resting NK cells was negatively correlated." (PMID 34376232, 2021). "Combining vaccine with rapamycin and anti-CTLA-4 decreases tumor growth and increases OVA-specific CD8+ T cells in the blood." (PMID 33802831, 2021). "In the indirect pathway, anti-PD-1/PD-L1 or anti-CTLA-4 reinvigorates T cell immunity, which, in turn, shapes or phenotypically polarizes innate immune cell responses within the tumor microenvironment (TME)." (PMID 33468555, 2021). "Interruption of these pathways with antibodies against targets including PD-1, its ligand programmed death ligand 1 (PD-L1) and CTLA-4 aim to facilitate a host immune response against the tumour, acting as immune checkpoint inhibitors (ICI)." (PMID 34640541, 2021). "In mice, subsets of tumor-derived MDSCs expressing PD-1 and CTLA-4 display decreased arginase 1 expression and activity upon CTLA-4 or PD-1 blockade in vitro." (PMID 33602280, 2021). "When mice bearing primary and distal CT26 tumor were treated with radiotherapy, anti-CTLA-4 Ab and PLGA-R837@Cat, primary tumors were eliminated, and secondary tumors disappeared." (PMID 33800368, 2021). "The combination of anti-CTLA-4 and anti-PD-L1 in this trial should address two different immune checkpoints in tumor-related immunosuppression, which has been shown to be effective in malignant melanoma." (PMID 33921668, 2021). "Despite growing evidence for the role of checkpoint receptors in NK cell-mediated anti-tumor responses, the expression of CTLA-4 in NK cells has been disputed in the literature for both mice and humans." (PMID 34376232, 2021). "A number of studies of antibodies blocking the cytotoxic T cell antigen 4 (CTLA-4) and thus intensifying the immune response against the tumor cells have been successfully completed." (PMID 34236546, 2021). "We investigated here for the first time on the cis-interaction between some Immune Checkpoints in tumor cells by using novel human anti-PD-1, anti-CTLA-4 and anti-PD-L1 mAbs." (PMID 34201082, 2021). "The tumor growth delay of mice that received [177Lu]Lu-DOTA-folate prior to anti-CTLA-4 antibody therapy was doubled, and, as a consequence, the survival time of mice substantially increased." (PMID 33078260, 2021). "We investigated the immunologic impact of combining dual CTLA-4 and PD-1 blockade with radiation and compared tumour immune infiltrates and therapeutic efficacy in the subcutaneous and orthotopic settings." (PMID 34784792, 2021). "Additional studies are required to identify the roles and mechanisms of exosomal CTLA-4 in tumor immunotherapy in the future." (PMID 34743730, 2021).
tumor (continued). "ICIs block immune checkpoints or immunosuppressive receptors, such as cytotoxic-T-lymphocyte-associated protein 4 (CTLA-4) and programmed death receptor-1 (PD-1) to improve the cytotoxicity and proliferative capacity of tumor-infiltrating lymphocytes (TILs)." (PMID 34451860, 2021). "Although ICB studies of anti-PD-1/PD-L1 and anti-CTLA-4 antibodies have significant advantages in multiple tumor treatments, there has been an increasing incidence of resistance to these antibodies in recent years." (PMID 33596985, 2021). "It however appears that both anti-PD-1 and anti-CTLA-4 are capable of inducing a profound remodeling of the tumor microenvironment via their engagement with different immune cell subsets." (PMID 33602280, 2021). "The clinical success of antibodies targeting CTLA-4 marks a significant milestone as these agents established immunotherapy as an emerging therapeutic modality of tumor treatment strategies next to surgery, chemotherapy, and radiation therapy." (PMID 34006227, 2021). "In particular, immune checkpoint inhibitors targeting PD-1, PD-L1, or CTLA-4 have been found to restore anti-tumor immune responses in some cancer entities, thus leading to profound therapeutic improvements in patients with advanced cancer diseases." (PMID 33430105, 2021). "Several antibodies targeting cellular immune checkpoints (PD-1/PD-L1 and CTLA-4) have been developed to determine the activation of T cells and subsequent tumor control." (PMID 34638281, 2021). "PD-L1 and CTLA-4, often used as tumor cell surface markers, can reduce the proliferation and effector function of the cytotoxic T cell (CTL) by binding to homologous receptors on the CTL." (PMID 34858852, 2021). "Regulatory T cells were almost exclusively found in tumor tissue samples and expressed inhibitory molecules such as CTLA4 and TIGIT (arrowheads) corresponding to their immunosuppressive role." (PMID 34663877, 2021). "Studies have shown that CTLA-4 inhibitors deplete Treg cells in the tumor, leading to enhanced effector function of antigen-specific T cells in the tumor." (PMID 33854960, 2021). "One mechanism by which Treg suppress the anti-tumor response is by interaction of CTLA-4 with CD80/CD86 on DC leading to a reduced expression of MHC class II, CD40 and CD86 molecules, all being important for Treg maturation and activation." (PMID 34638420, 2021). "The study demonstrated that elevated tumor-distinct expression of MHC-I was pivotal for the response to therapy with anti-CTLA-4." (PMID 34336848, 2021). "In mice, OncoVEXmGM-CSF (mT-VEC) in combination with anti-CTLA-4 significantly extended survival compared to single treatments alone in both A20 and CT-26 bilateral tumor models, with a significant increase in tumor-specific splenocytes." (PMID 34578321, 2021). "MAIT cells from HCC tumours expressed higher levels of the inhibitory markers PD-1, CTLA-4 and TIM-3 when compared to healthy liver." (PMID 33808058, 2021). "Blockade of CTLA4 has been shown to increase the infiltrative T cell and decrease Treg response to tumor cells by allowing the co-stimulatory receptor CD28 to bind CD80 (B7.1) and CD86 (B7.2) expressed on antigen-presenting cells (APC)." (PMID 34976006, 2021). "In a pre-clinical model of PDAC, peri-tumoral anti-CTLA4 has demonstrated effective inhibition of tumor growth, with increased effector T-cell infiltration and reduced Tregs." (PMID 33864144, 2021). "Both RT schedules were equally ineffective in controlling the tumor growth when delivered as single agent therapy, and durable tumor control was only observed in combination with anti-CTLA-4 mAb." (PMID 33530329, 2021). "Combining CSF1R blockade with anti-PD-1 or anti-CTLA-4 inhibitors showed improved tumor response compared with single-arm anti-PD-1 or anti-CTLA-4 treatment." (PMID 33922556, 2021).
tumor (continued). "In this study we demonstrate that Lef treated tumors demonstrated decreased CTLA-4 + T cells indicating a decrease in intratumoral T cell exhaustion and perhaps more anti-tumor immunity." (PMID 34239352, 2021). "In tumor bearing murine models exposed to anti-CTLA-4, Tregs are found to expand in the periphery, whilst simultaneously being depleted in the TME." (PMID 33602280, 2021). "This is caused by various mechanisms such as reduced HLA class I expression and secretion of immunosuppressive cytokines of tumor cells, T-cell anergy of peripheral T-cells and TILs and overexpression of PD-1 and CTLA-4." (PMID 34067112, 2021). "Modest synergy was seen when G47ΔV-mIL-12 was combined with single agent ICPI (PD-1 or CTLA-4), however triple therapy (OV/PD-1/CTLA-4) led to long-term cures and protection from tumour re-challenge." (PMID 34733287, 2021). "Drug Administration (FDA) for mRCC include those that block co-inhibitory molecules, such as cytotoxic T-lymphocyte activating protein-4 (CTLA-4), PD-1, and PD-L1, thus facilitating T cell effector function and anti-tumor response." (PMID 34208157, 2021). "PD-1 acts in the late stage of T-cell activation, after T-cell migration into the tumor microenvironment, while CTLA-4 acts in the early stage of T-cell activation." (PMID 34869005, 2021). "In the preclinical setting, a recent study characterized the inflammation-induced neurological dysfunction by radiotherapy to tumor bearing hind flank of mice in combination with anti-CTLA4 blockade in preclinical models." (PMID 33658642, 2021). "On account of CTLA-4 expression in MCC, tumor cells are vulnerable to anti-CTLA-4 antibody treatment." (PMID 34208339, 2021). "The principle of ICIs is to reactivate immune cells by using specific antibodies against inhibitory signaling molecules such as CTLA-4 and PD-1 expressed on tumor and immune cells." (PMID 34970479, 2021). "PD-L1 and CTLA-4 immune checkpoint pathways are potent inhibitors of tumour-reactive T cell activation, clonal expansion and subsequent tumour rejection." (PMID 35047074, 2021). "The anti-tumor effects of anti-CTLA-4 antibody were similarly compromised in mice treated with a broad-spectrum antibiotic cocktail to eliminate the intestinal microbiome." (PMID 34162429, 2021). "Checkpoint inhibitors mainly work by targeting the negative regulators of T cell function, such as CTLA-4, PD-1, and PD-L1, unleashing T-cells and allowing them to induce tumor cell death." (PMID 34203478, 2021). "Intriguingly, we observed that Sunitinib had synergistic effect with CTLA‐4 mAb which significantly inhibited tumor growth and prolonged the OS rate by promoting immune surveillance." (PMID 33510997, 2021). "The same study reported the failure of Salmonella and anti CTLA-4 combination in treating tumor-bearing mice." (PMID 34203478, 2021). "Pvr-KO tumors grew slightly slower than wild-type tumors, and combination with anti-PD-1 and anti-CTLA-4 mAbs inhibited pvr-KO tumor growth." (PMID 34795004, 2021). "The ability to induce tumor regression in murine models by blocking the prototypical receptor CTLA-4 was discovered over 20 years ago." (PMID 33596985, 2021). "We also analyzed the prognostic role of CTLA-4 expression in tumor cells (TumorCTLA-4) in patients with ICC." (PMID 34526987, 2021). "Compared to the control group, the volume and weight of the transplanted tumor were significantly less in the CTLA-4 inhibition group." (PMID 34553071, 2021). "CTLA-4 inhibition was shown to induce tumor infiltrating and circulating 4PD1Hi cells, whereas anti-PD-1 treatment exerted an opposite effect on this cell subset." (PMID 33602280, 2021). "The levels of Ki-67 expression in the CX3CR1+ CD8+ T cells were significantly higher than in the CX3CR1−(CD27lo CX3CR1− and CD27hi CX3CR1−) subsets 2 weeks after anti-CTLA-4/PD-L1 therapy in CT26 tumor-bearing mice." (PMID 33658501, 2021).
tumor (continued). "They differ from CTLA-4 in that they regulate primed T-cell activity in peripheral tissue and the tumor microenvironment (TME)." (PMID 34000441, 2021). "By looking at the optimal protocols, the vaccine allows one to reduce the anti-CTLA4 dosage while reaching the goal of tumor eradication." (PMID 35008298, 2021). "We also demonstrated efficacy with a combinatorial strategy consisting of a GM-CSF-secreting tumor cell vaccine and ICB therapy (anti-PD-1 and anti-CTLA-4) in mice bearing ID8-VEGF-expressing tumor." (PMID 34572778, 2021). "The percentage of NK cells out of tumor infiltrating lymphocytes (CD45+) was increased in tumors of mice treated with anti-CTLA-4 and BEMPEG as compared to all other groups (p<0.01)." (PMID 33937052, 2021). "PD-L1 and cytotoxic T-lymphocyte-associated protein 4 (CTLA-4), arginase 1 (ARG1), high-mobility group box 1 protein (HMGB1), and TGF-β are among the proteins found in tumor cell exosomes related to immunosuppression." (PMID 34685513, 2021). "Anti-PD-1, anti-PD-L1 and anti-CTLA-4 monoclonal antibodies also enhance NK cell tumour trafficking and release cytokines against tumours whilst simultaneously supressing Treg function." (PMID 33995362, 2021). "Some studies have reported that subcutaneously implanted Pan02 tumor-bearing mice respond significantly well to anti-PD-1/PD-L1 and anti-CTLA-4 antibody treatment." (PMID 33503832, 2021). "Eosinophils were also found to be potentiators of anti-CTLA4 therapy in breast cancer patients, being correlated with their level of accumulation within the tumor." (PMID 33418996, 2021). "We found that combination of α-IL-6 and α-CTLA-4 further inhibited tumor growth compared to IgG control groups and other single treatments." (PMID 34093869, 2021). "Studies have found that tumor-derived exosomes carry immunosuppressive proteins, such as PD-1, CTLA-4, FasL, TRAIL, etc.." (PMID 34744733, 2021). "Circulating tumor cells can activate a cytotoxic T-cell response in the liver, promoting immune surveillance evasion via inhibitory molecules such as CTLA-4 or PD-1." (PMID 33800796, 2021). "Tumor cells use mechanisms that act via the PD-L1 or CTLA-4 program, a blockage of co-stimulation to activate T cells, and the recruitment of tumor-associated macrophages and marrow-derived suppressor cells (MDSCs), to achieve immune suppression." (PMID 34359820, 2021). "CTLA-4 blockade can then provide long-lasting tumour remission due to its impact on memory T cells response to cancer." (PMID 33995362, 2021). "In two mouse models of breast (4T1) and colon (CT26) cancer, MWA of primary tumours followed by combined anti-PD-1 and anti-CTLA-4 treatment resulted in prolonged survival compared with MWA or ICPIs alone." (PMID 34733287, 2021). "For example, ICT, which aims to target molecules highly expressed in tumours, such as PD-L1/PD-1 and CTLA-4, to reduce the depletion of effector T cells, is especially effective in SKCM and NSCLC." (PMID 34753903, 2021). "Of particular interest, a single patient with prolonged partial response to ipilimumab (CTLA4 blockade) exhibited TLS within their tumor sample." (PMID 34267760, 2021). "Immune checkpoint-blocking antibodies, including anti-CTLA-4 and anti-PD-1, can induce tumor responses in a variety of tumor types." (PMID 34721758, 2021). "NCT03517488 studies the use of anti-PD-1 and anti-CTLA-4 to reactivate tumor lymphocytes in advanced HCC." (PMID 34696292, 2021). "The Food and Drug Administration (FDA) has so far approved seven ICIs that target cytotoxic T-lymphocyte antigen 4 (CTLA-4), programmed death-1 (PD-1) and PD-ligand 1 (PD-L1) for the treatment of several tumor types." (PMID 33467713, 2021). "When the CTLA4 binds to its ligands, the T cells become deactivated and fail to mount the immune responses to infections and tumours." (PMID 33921181, 2021).